IDH1 (isocitrate dehydrogenase (NADP(+)) 1)
Diseases named in the same sentence as IDH1 in open-access papers (continued):
Sharing a sentence is not in itself a finding about the gene and the disease.
tumor (continued). "The small number of patients harbouring non-R132H IDH1/2-mutated tumours (n = 11) may also mask potential survival differences." (PMID 33740099, 2021). "Tumor-derived IDH1 and IDH2 mutations not only simultaneously lose their normal catalytic activity: the production of α-ketoglutarate (α-KG) from the convertion of isocitrate, but also gain a neomorphic enzymatic activity: the reduction of α-KG to D-2-hydroxyglutarate (D-2-HG)." (PMID 34079802, 2021). "Perfusion-weighted and/or diffusion-weighted MRI features have been used to predict EGFR amplification and MGMT-methylation, whereas MR spectroscopy and amino acid tracer PET imaging (FET–PET) can predict IDH1 mutation status due to its effects on tumor metabolism." (PMID 33578746, 2021). "Beyond IDH1 mutation, which represents the earliest genetic alteration in LGG, longitudinal analyses at relapse have evidenced a high mutational potential of this tumor, especially with possible clonal expansion and epigenetic reprogramming after deletion or amplification of mutant IDH1." (PMID 34638248, 2021). "Two patients with an IDH1-mutated tumor had a D/L-2HG ratio lower than 4.5." (PMID 34069550, 2021). "The clinical data of the 87 CRC patients with high IDH1 expression tumors and 38 patients with low IDH1 expression tumors showed that high IDH1 expression was associated with a high-stage tumor (p < 0.001), distant metastasis (p = 0.006) and lymph node metastasis (p = 0.002)." (PMID 34234856, 2021). "Interestingly, IDH1 action relies on the conversion of isocitrate to alfa-ketoglutarate; in case of IDH mutations, alfa-ketoglutarate is transformed by IDH1 into 2-hydroxyglutarate (2-HG), which plays a role in tumor progression." (PMID 32878011, 2020). "In patients with glioma, the IDH1 R132H mutation was identified in plasma with a specificity of 100% and sensitivity related to the tumor volume and contrast enhancement, suggesting that it may help in the diagnosis of patients not amenable to biopsy." (PMID 32010431, 2020). "Importantly, the prompted cell migration and endocytosis reprogrammed the food-seeking pattern in IDH1-mutated cancer cells, which, in return, supported tumor cell progression." (PMID 32224866, 2020). "A significant association was found between IDH1 mutation and tumor location." (PMID 32856857, 2020). "Moreover, the typical case described in methods who reached long-term (20 months) SD after treated with dasatinib also proved that ICC patient with IDH1/2 mutation had a better prognosis, even if the tumor is of advanced stage." (PMID 32293336, 2020). "Therefore, a case of GBM with IDH1 mutation in our study suggest that the tumor has developed from a lower grade (secondary GBM)." (PMID 33282092, 2020). "Two tumors (17%) had EGFR amplifications and 1 tumor (8%) had an IDH1 R132H mutation." (PMID 33063013, 2020). "Tumor cells reshape their metabolism in order to sustain their rapid growth and this remodeling can be further modified in those cases where mutations occur in pivotal metabolic enzymes, such as IDH1." (PMID 32575619, 2020). "The IDH1 R132H mutation was identified in plasma (specificity, 100%; sensitivity related to the tumor volume and contrast enhancement).It may help in the diagnosis of patients not amenable to biopsy." (PMID 32010431, 2020). "LSP1 expression also had a close association with IDH1 wild type tumor, and could be used as an indicator for the survival of GBM patient with radio- and chemotherapy." (PMID 32003759, 2020). "These outcomes match with the corresponding IDH1 mutations detected in tumor tissues." (PMID 31968687, 2020).
tumor (continued). "Interestingly the subgroup analysis showed significant improvement in survival in patients with IDH1/2 mutated tumours (2-year OS 90%, 95% CI, 73%–99%) vs. wild-type tumours (2-year OS 33%, 95% CI, 18%–63%)." (PMID 32423017, 2020). "However, the mechanism of IDH1 mutation and the significance of prognosis in tumor growth were still unclear." (PMID 32582544, 2020). "We stratified these tumor specimens by their IDH1 mutation status and focused on the DEGs." (PMID 32224866, 2020). "Thus, we also investigated the relationship of MGMT promoter methylation and IDH1/2 mutation status with multifocal tumor growth and tumor contact to the SVZ." (PMID 34966832, 2020). "Interestingly, IDH1, which also plays a protective role in the tumor-associated redox process, has been recently proposed as a promising plasma biomarker for the diagnosis of lung ADC." (PMID 32575471, 2020). "The IDH1 mutation causes an increase in SCD activity in the tumor." (PMID 32392704, 2020). "Altogether, these studies suggest that IDH1/2 mutations disrupt the chromosomal topology and orchestrate a complete change in the expression profile of the tumor cells, promoting tumor growth through the induction of oncogenic molecules and the inhibition of pro-differentiation genes." (PMID 32570988, 2020). "Accordingly, molecular profiling of CCA tumours has become increasingly significant over the past few years due to the identification of potentially druggable molecular alterations, such as mutations in IDH1/2 and FGFR2 fusions." (PMID 32694694, 2020). "Therefore, researchers have examined tumor-forming capacity by induction of additional oncogenic mutations in conjunction with IDH1 mutation." (PMID 33552990, 2020). "Here, we report that tumor-derived IDH1 mutation sensitizes cells to ferroptosis." (PMID 31591388, 2019). "The IDH1/2 mutations make the tumor microenvironment easier to form." (PMID 31263678, 2019). "This prognostic effect could not be explained by treatment with specific anti-epileptic drugs, a smaller tumor volume at presentation, due to an earlier detection of the tumor, or IDH1 mutations." (PMID 30621209, 2019). "The IDH1 synthetic long peptide is an example of a rationally designed neoantigen vaccine based on a tumor-specific point mutation shared by a large patient population with a mildly immunogenic tumor." (PMID 31040852, 2019). "In the present study, we found that age and the tumor volume may be used to indicate IDH1 mutation status in GBM patients with a high degree of diagnostic performance." (PMID 31275753, 2019). "Tumor cells were positive for IDH1 mutation and positive for MGMT methylation status." (PMID 31929892, 2019). "IDH1 (R132H) encodes a neoantigen widely and prematurely expressed by all tumor cells." (PMID 30708988, 2019). "In summary, we found that the IDH1 mutation status may be determined using a combination of age and tumor volume in patients who are diagnosed with GBM via traditional medical imaging methods." (PMID 31275753, 2019). "However, the observation that the IDH1 mutation impairs cell proliferation seems incompatible for a tumor-promoting event." (PMID 31888244, 2019). "In addition, several studies have showed that the IHC antibody raised against mutant IDH1 protein with R132H mutation can specifically recognize this mutant protein in the tumor tissues using immunochemistry staining (IHC)." (PMID 29661250, 2018). "IDH1 R132H mutation was assessed by RT-PCR from FFPE tumor samples obtained during surgery." (PMID 29662659, 2018). "Importantly, the decreases in miR-29a/b/c levels were significantly associated with the wild-type IDH1/2 gene, older age, advanced tumor grade, and higher Ki-67 LI (P < 0.0001)." (PMID 30348972, 2018). "This can serve as a surrogate marker for all tumor relevant IDH1 and IDH2 mutations." (PMID 29499756, 2018). "This supports the notion that IDH1 mutation alone may be insufficient to promote tumor formation and other genetic alterations are required." (PMID 29953513, 2018).
tumor (continued). "Our model systems help understand the biology of IDH1 mutations and its role in tumor formation." (PMID 29953513, 2018). "However, few data are available about the bioenergetic consequences of IDH1 mutation and their role in growth and survival of tumour cells." (PMID 30404651, 2018). "The R132H IDH1 mutation was observed in 8 of 65 tumor samples (12.31%)." (PMID 28785587, 2017). "IDH1 mutations were identical in both tumor regions in all 4 cases." (PMID 28270234, 2017). "Known metabolic alterations (IDH1/2 mutation) are able to reshape the tumor methylome and may also affect specific traits of tumor gene expression." (PMID 28380457, 2017). "We further extend our study to explore future treatment options for IDH1 mutated tumor." (PMID 28052098, 2017). "In recurrent tumours, all 22 (22/48, 45.83%) of the detected IDH1 mutations were R132H (CGT-CAT)." (PMID 29026176, 2017). "We here report the analysis of mutations in genes encoding the metabolic enzymes IDH, SDH and FH in a cohort of ~100 central cartilaginous tumours, and demonstrate that the prevalence of mutations in IDH1 or -2 is ~60%, which is comparable to previously published data." (PMID 28484589, 2017). "Therefore, XAF1 methylation does not represent an independent prognostic marker in this particular tumor entity but provides a surrogate marker of IDH1 and probably IDH2 mutations." (PMID 28122345, 2017). "In the H3/IDH1 mutant tumor HGG5, a PDGFRA Y288C missense mutation was acquired at recurrence." (PMID 29084603, 2017). "However, continued oxygen use in hypoxia is likely to create highly challenging conditions in an IDH1‐mutated tumor, as it is likely to further exacerbate the hypoxic microenvironment, potentially leading to increased areas of necrosis." (PMID 27196610, 2016). "IDH-1-mutated tumor patients display either increased or decreased CD4-positive lymphocytes." (PMID 27585656, 2016). "Analysis of IDH1 mutations was performed in 330 tumor samples." (PMID 26556853, 2016). "Moreover, putative IDH1 mutations, which were detected with a mutation specific IDH1 antibody by immunohistochemistry, need to be interpreted carefully as only tumor samples with intense immunoreactivity were mutated within the pyrosequencing analysis." (PMID 27253461, 2016). "In all likelihood, mutations in IDH1 will exert a myriad of context-dependent effects to varying consequence depending on the origin of the tumour, the stage of the disease, the oxygen tension within the tumour and the duration of the disease." (PMID 27820599, 2016). "Whether these differences may be in part due to tumor-related factors such as IDH1/2 mutations and MGMT promoter methylation is unclear due to the small number of subjects." (PMID 26910903, 2016). "Second, neoantigens expressed by tumor tissues such as mutated IDH-1 may be responsible for the activation of CD8 expressing lymphocytes and a measurable effect on better survival." (PMID 27585656, 2016). "This suggests that activation of mTORC1 occurs downstream of the PI3K–PDK1–AKT cascade in tumours harbouring IDH1 mutations, supporting the notion that 2HG-mediated inhibition of KDM4A affects the stability of DEPTOR leading to mTOR activation independently of the PI3K/AKT/TSC1-2 pathway." (PMID 27624942, 2016). "Mutation of the gene IDH1 was associated with a patient’s longer survival, and linked with patterns of mRNA expression and DNA methylation across several hundred genes and genomic regions, respectively, in the tumor’s genome." (PMID 27798635, 2016). "The IDH1-R132H mutation was detected by immunohistochemistry in 18 tumours (49%)." (PMID 25849605, 2015). "Taken together, these results suggest that while mutation of the IDH1 gene may initially drive tumourigenesis, it actually slows tumour growth by reducing cell proliferation." (PMID 25849605, 2015).
tumor (continued). "We sought to determine whether pathological and/or radiological variables exist that can reliably distinguish IDH1-R132H-positive from IDH1-R132H-negative tumours and to identify variables associated with early mortality." (PMID 25849605, 2015). "Moreover, growing evidences indicate that oncogenesis of IDH1 mutated tumor involves reduced production of NADPH as well as oncometabolite of 2HG production." (PMID 26008980, 2015). "Thus, in addition to the accumulation of D2-HG in IDH1/2 mutant tumours, the related metabolite, L2-HG, has also been linked to cancer." (PMID 26178471, 2015). "Furthermore, even a three-fold reduction of D-2-HG was sufficient to suppress tumor growth of IDH1-mutated HT1080 cells." (PMID 25825982, 2015). "Alternatively, because the IDH1 mutation is known to be an early event in tumor development, it is possible that the biopsy findings reflect additional events that occur during tumor development subsequent to the IDH1 mutation and that are not reflected in our models." (PMID 25706986, 2015). "In addition, accumulating research has confirmed that IDH1 mutation occurs early in gliomagenesis, which suggests that this genetic event drives tumor progression." (PMID 26115094, 2015). "The mechanism of through which IDH-1 mutation effect tumor outcomes is not well understood." (PMID 26015297, 2015). "Our observations that D-2-HG is required for tumor growth of cancer cells with IDH1/2 mutations suggest that inhibition of mutant IDH1/2 could be an attractive strategy for therapeutic treatment of cancers with IDH mutations." (PMID 25825982, 2015). "To date, few studies have focused on the association between tumor location and IDH1 mutation." (PMID 26115094, 2015). "All three tumours demonstrating a loss of 1p or 19q were also IDH1-R132H positive." (PMID 25849605, 2015). "Mutations in IDH1 were also identified in substantial portion of other tumor types." (PMID 24511544, 2014). "We conducted univariate Cox regression analysis using clinical and genetic variables for the independent cohorts and observed that Rab27a expression, preoperative KPS score, tumor resection extent, and IDH1 mutation status were significantly associated with OS." (PMID 24587032, 2014). "Given the right context, it seems those two structurally related but different metabolites converge on a phenotype that gives an increased risk of malignancy, both in a child with an inborn error of metabolism and an adult with IDH1 or IDH2 mutations confined to the tumor." (PMID 24581008, 2014). "The examined mutation IDH1 R132H was observed in 20 of 44 GBM-patient tumor samples." (PMID 24511544, 2014). "Whether mutations in IDH1 promote or inhibit cell proliferation and survival depends on the tumor site." (PMID 25277207, 2014). "Candidate epigenetic driver genes have been identified as either mutated across many cancers (e.g. KDM6A in over 12 cancers), having highly recurrent mutations (e.g. IDH1 R132), or having highly prevalent mutations in select tumor histologies (e.g. MLL2 in follicular lymphoma)." (PMID 24622842, 2014).
tumor (continued). "Together with the fact that IDH1 mutation is an early event in gliomagenesis, its constant statusthroughout the tumor evolution and absenceof association with malignant transformation suggest that IDH1 mutation is likely involved in tumor initiation instead of malignant progression." (PMID 23840696, 2013). "In conclusion, the current study provided evidence that IDH1 mutation was frequently detected in LGGs, and IDH1 mutation may result in tumor-related seizures." (PMID 24324372, 2013). "The IDH1 mutational status remained unchanged at second surgery in all 12 tumor pairs." (PMID 23826216, 2013). "In the first test, we analyzed cell populations for the IDH1/2 mutation of the primary tumor." (PMID 24349039, 2013). "The E478 xenograft line represents a stable tumor model with the endogenous IDH1-R132H mutation." (PMID 24252742, 2013). "It has been suggested that pseudopalisades represent a wave of tumor cells actively migrating away from central hypoxia, the driving force for which may be the IDH1 mutation found in association with this abnormality in the present study." (PMID 23451042, 2013). "To assess whether mutant and wild type IDH1 contribute to IDH1 mutated tumor cell growth, we created an IDH1 inducible knockdown cell line utilizing the fibrosarcoma cell line, HT1080 which harbors a heterozygous IDH1R132C mutation." (PMID 22885298, 2012). "However, even though special care was taken to ensure tumor tissue for DNA extraction, it cannot be completely excluded that the IDH1- mutations in the recurrent tumors merely escaped detection." (PMID 22844452, 2012). "This underscores the notion that IDH1- mutations are a decisive factor for tumor initiation." (PMID 22844452, 2012). "To date, few reports pointed out that IDH1 mutations were associated with tumor locations." (PMID 22291938, 2012). "The IDH1- mutational status changed in the recurrent tumor of three tumor pairs (6%)." (PMID 22844452, 2012). "Besides, some studies identified an association between the incidence of 1p/19q co-deletion, IDH1/2 mutation and tumor locations." (PMID 22427879, 2012). "In addition to this study, depicting HIF as a sort of “bystander player” in the onset of tumors harboring FH mutations, another report indicated this transcription factor as a tumor-suppressor protein in tumors carrying IDH1/2 mutations." (PMID 22888353, 2012). "Because of the specificity of mutant IDH1 to tumor cells and its absence in the surrounding parenchyma, drugs specifically designed to disrupt mutant IDH1 may kill tumor cells with IDH1 mutations while sparing normal tissues." (PMID 22885298, 2012). "This phenomenon indicates that there might be a direct relationship between IDH1 mutations and tumor location." (PMID 22291938, 2012). "Therefore, it is possible that IDH1/2 mutations were involved in oncogenesis by the inactivation of tumor suppressor genes through promoter hypermethylation." (PMID 22291938, 2012). "Ninety tumour samples were found to stain for the mutated IDH1 R132H protein." (PMID 21559010, 2011). "IDH1 mutations are associated with the CpG island hypermethylation phenotype (MvdB and PF, submitted), and promoter hypermethylation in cancer often occurs in the promoter regions of tumor suppressor genes." (PMID 21760942, 2011). "Mutations in IDH1 are thought to occur early in tumorigenesis, with recent evidence suggesting IDH1 mutations may have tumor promoting functions." (PMID 22046342, 2011). "Due to the potential importance for the CDKN2A C500G polymorphism and IDH1 mutations in GBM, the current study investigated the C and G 500 allele frequencies in genomic DNA, and IDH1 mutations in tumor DNA from 107 individuals with telomerase, ALT, and NDTMM GBMs." (PMID 22046342, 2011). "This may support recent linesof evidence that IDH1/2 mutations may be causal of tumour initiation in germlinesyndromes such as hydroxyglutaric aciduria." (PMID 21317451, 2010).